SNORA11G (small nucleolar RNA, H/ACA box 11G)
Gene: Small nucleolar RNA gene on chromosome X (54,927,305 to 54,927,433, forward strand). Ensembl gene ENSG00000221750.
Gene Ontology:
Biological process: RNA processing
Cellular component: nucleolus
Homologues: Orthologues: chimpanzee SNORA11G (100% identical), macaque SNORA11G (99% identical), pig SNORA11G (91% identical), rabbit SNORA11G (89% identical), guinea pig SNORA11G (71% identical), mouse Gm24907 (68% identical), rat LOC120099525 (58% identical), mouse Gm24595 (53% identical). Paralogues in human: SNORA11C (75% identical), SNORA11F (75% identical), SNORA11B (74% identical), SNORA11D (74% identical), SNORA11E (74% identical), SNORA11 (73% identical).